PTGS2 (prostaglandin-endoperoxide synthase 2)
Diseases named in the same sentence as PTGS2 in open-access papers (continued):
Sharing a sentence is not in itself a finding about the gene and the disease.
atherosclerosis (61 papers, 2007 to 2025). A disease characterized by the build-up of fatty material and calcium deposition in the arterial wall resulting in partial or complete occlusion of the arterial lumen. "Among which, a reporter said that PTGS2 expression was upregulated in advanced stages of atherosclerosis, and positively associated with severity of atherosclerosis." (PMID 37476576, 2023). "NFE2L2 is associated with atherosclerosis, AR is associated with coronary artery disease, and PTGS2 is associated with myocardial infarction." (PMID 36188612, 2022). "PTGS2 has been linked to atherosclerosis, stroke, and other CVDs." (PMID 33628326, 2021). "In advanced atherosclerosis stages, prostaglandin endoperoxide synthase 2 (PTGS2), ACSL4, caspase-1, and NOD-like receptor protein 3 (NLRP3) expression is upregulated, while GPX4 is downregulated." (PMID 40308274, 2025). "These markers' expression correlates with atherosclerosis severity, with PTGS2 demonstrating potential as a key gene." (PMID 40308274, 2025). "Given its central role in mediating inflammatory responses within vascular tissues, PTGS2 represents a potential therapeutic target for modulating disease progression in atherosclerosis and possibly other related vascular disorders." (PMID 39239552, 2024). "PTGS2 was downregulated in the late stage of atherosclerosis, and the expression of PTGS2 was positively correlated with the severity of atherosclerosis." (PMID 37283588, 2023). "During the late stage of atherosclerosis, the levels of the iron ferroptosis-related proteins PTGS2 and ACSL4 are increased, while GPX4 expression is decreased." (PMID 37181809, 2023). "In the study of Zhou, they found PTGS2 is upregulated in atherosclerosis, which illustrated that the factor is involved in the early inflammatory response of blood vessels in some way." (PMID 37238642, 2023). "Analysis of network pharmacology and molecular docking confirmed that AKT1, caspase-3 (CASP3), MAPK1, MAPK3, NOS2, and prostaglandin-endoperoxide synthase 2 (PTGS2) were GZFL's potential target genes against atherosclerosis." (PMID 35529925, 2022). "PTGS2 metabolizes AA to produce prostaglandin and thromboxane, which influence platelet aggregation, vascular wall tension, and atherosclerosis." (PMID 36523490, 2022). "PTGS2 is generally accepted to promote atherosclerosis; however, it also protects against myocardial ischemia/reperfusion injury." (PMID 36523490, 2022). "PTGS2 is involved in various signal transduction pathways involved in pain, inflammation, tumor neoplasia, atherosclerosis, and coronary heart disease." (PMID 34746316, 2021). "Together, these findings strongly indicate that galectin-3 acts as a negative regulator of inflammation by modulating TGFβ signaling and reducing the expression of the proinflammatory molecules MMP12, CCL2, and PTGS2 in a mouse model of atherosclerosis." (PMID 32295421, 2020). "On the other hand, atherosclerosis related hsa-miR-143-3p targets in VSMCs included CACNA1C, COL1A1, and PTGS2, which are associated with VSMC contraction, extracellular matrix synthesis, and proliferation." (PMID 32397522, 2020). "Furthermore, the severity of atherosclerosis was positively correlated with the expression of Ptgs2 and ACSL4 and negatively correlated with the expression of GPX4." (PMID 36192693, 2022). "Our finding that GBH contains five core compounds (quercetin, kaempferol, baicalein, ellagic acid, and baicalin) that can be linked to six potential target genes (AKT1, CASP3, MAPK1, MAPK3, NOS2, and PTGS2) related to atherosclerosis is in agreement with previous reports." (PMID 33321972, 2020). "Thus, the inhibition of PTGS2 is essential for the restoration of PBMCs activity and in the process of atherosclerosis." (PMID 26813334, 2016).
atherosclerosis (continued). "Moreover genes encoding for a variety of proteins that have been associated with atherosclerosis were up-regulated including phospholipase A2 (PLA2G4C), prostaglandin synthase 2 (PTGS2) also known as cyclooxygenase-2, thrombin receptor like-1 and the gene encoding for superoxide dismutase 2 (SOD2)." (PMID 17534423, 2007). "For example, a study found that two ferroptosis-related proteins, PTGS2 and ACSL4, and two necroptosis-related proteins, NLRP3 and caspase-1, are upregulated in the advanced stages of atherosclerosis (AS) and are positively correlated with the severity of AS." (PMID 39072329, 2024). "The expression of PTGS2 and ACSL4 in human coronary artery specimens is positively correlated with the severity of atherosclerosis." (PMID 39396974, 2024). "The molecular activity prediction analysis showed that TQ inhibition of IL-6 significantly attenuated the levels of Akt, NF-kB Complex, Ap1, ERK 1⁄2 STAT5 a/b, PTGS2, PI3K Complex, XIAP, and estrogen receptor in atherosclerosis." (PMID 35723378, 2022). "There were six targets in the intersection with 137 candidate therapeutic targets of XFZYD, which included upregulated PTGS2, MMP9, and BCL2L1 and downregulated JUN, VEGFA, and CXCL2 in the atherosclerosis group." (PMID 33425996, 2020). "PTGS2, also known as COX-2, is upregulated in the macrophages of atherosclerotic lesions and may augment the inflammatory response in atherosclerosis." (PMID 37090698, 2023). "Three key pathways (pathways in cancer, the TNF signaling pathway, and lipid and atherosclerosis) and the top six anti-COVID-19 core targets (IL-6, PPARG, MAPK3, PTGS2, ICAM1, and MAPK1) were determined to be involved in the treatment of COVID-19 with active phytomolecules of Kochiae Fructus." (PMID 35992697, 2022). "Overexpression of PTGS2 is associated with multiple inflammatory diseases, and considering inflammation as a key element in the development of atherosclerosis and CHD, the activity of PTGS2 may influence the progression of CHD by modulating the inflammatory response." (PMID 40629647, 2025).
rheumatoid arthritis (48 papers, 2008 to 2026). A chronic, systemic autoimmune disorder characterized by inflammation in the synovial membranes and articular surfaces. "The prostaglandin endoperoxide synthase 2 gene was associated with rheumatoid arthritis via pathway verification and monitoring of human gene expression levels." (PMID 36435778, 2022). "On the other hand, PTGS2, also known as cyclooxygenase-2, is a well-known pathological factor whose increased expression in osteocytes of the subchondral bone is associated with both OA and rheumatoid arthritis (RA)." (PMID 38328576, 2023). "Treatment with PTGS2 has been shown to reduce inflammation in rheumatoid arthritis rats by reducing serum levels of interleukin 1β, interleukin six and tumor necrosis factor α and their mRNA expression." (PMID 36923645, 2023). "Several of the induced genes, particularly proinflammatory cytokines IL1β, IL6, and PTGS2 and genes involved in antigen presentation (HLA-DRB1), have been implicated in persistent inflammation in other conditions including atopic dermatitis, psoriasis, and rheumatoid arthritis." (PMID 41333458, 2025). "In support of our observation, the PTGS2 gene promoter has NF-κB and AP-1 binding sites, and activated p65 and c-Jun could induce PTGS2 expression in several cell types, including human cervical cancer cells and human rheumatoid arthritis synovial fibroblasts." (PMID 31527064, 2019). "Downregulation of PTGS2 reduces the expression of IL-6 and MMP-3, and the downregulation of MMP-3 and PTGS2 have been shown to help inhibit synovial fibroblast proliferation and joint inflammation in rheumatoid arthritis." (PMID 34917160, 2021).
pancreatic cancer (46 papers, 2005 to 2025). "Our findings, overall, align with a study that demonstrated tumor cell-intrinsic EphA2 inhibits anti-tumor immunity in pancreatic cancer through the regulation of PTGS2, the gene encoding cyclooxygenase-2 (COX2)." (PMID 40867322, 2025). "The intrinsic TGF-β signaling of pancreatic tumor cells induced the overexpression of PTGS2, leading to decreased level of activated CD8 + T cells in the TME." (PMID 38520006, 2024). "In pancreatic cancer, knocking out PTGS2 or using its inhibitors can help the tumor to be sensitive to immunotherapy." (PMID 34124047, 2021). "In another study, the presence of stromal fibroblasts increased pancreatic cancer cell expression of a set of genes linked to tumor cell invasion, including cyclooxygenase 2 (COX-2)/prostaglandin-endoperoxide synthase 2 (PTGS2), hyaluronan synthase 2 (HAS2), and matrix metalloproteinase-1 (MMP-1)." (PMID 29903049, 2018). "Except for IGFBP3 which hadn’t been found in HPA, as we predicted, protein expressions of PTGS2 (p < 0.01) and TOP2A (p < 0.001) were higher in pancreatic tumor tissue, which was consistent with their correlation with poor survival of PAAD patients." (PMID 36003146, 2022). "Markosyan and his colleagues identified PTGS2 was upregulated by EPHA2, a candidate tumor intrinsic driver of immunosuppression, through TGF-β pathway in pancreatic cancer." (PMID 33718229, 2021). "Interestingly, the expression of PACERR and PTGS2 in sham group macrophages was very low and upregulated after THP‐1 co‐culture with pancreatic cancer cells." (PMID 35184402, 2022). "In conclusion, our data demonstrate that chronic ethanol exposure of HPNE cells induces EMT in vitro, and oral ethanol feeding of KC mice promoted pancreatic cancer growth and development by regulating SATB2, inflammatory cytokines, PTGS‐2, stem cell markers, and pluripotency‐maintaining factors." (PMID 34859959, 2022). "Our data demonstrate that chronic ethanol exposure can induce EMT and oral ethanol feeding of KC mice promotes pancreatic cancer growth and development by regulating SATB2, inflammatory cytokines, PTGS‐2, stem cell markers, and pluripotency‐maintaining factors." (PMID 34859959, 2022). "Since ethanol feeding of KC mice promotes pancreatic cancer growth and development, we next sought to measure the expression of stem cell markers, pluripotency‐maintaining factors cadherins, EMT‐transcription factors and inflammatory cytokines, and PTGS‐2 gene in KC mice." (PMID 34859959, 2022). "Curcumin was shown to suppress growth of bladder and pancreatic cancer cell lines through the inhibition of NFKB1-regulated proinflammatory and proproliferative gene products PTGS2 and CXCL8; both CXCL8 and PTGS2 were also found to be downregulated in pancreatic cancer." (PMID 34422220, 2021).
Arthritis (45 papers, 2007 to 2026). Inflammation of a joint. "Taken together, these results indicated that Robo4 suppressed Ptgs2-associated inflammatory conditions such as arthritis, edema, and pain." (PMID 38762541, 2024). "In rodents, the ROBO4-TRAF7 complex also suppresses prostaglandin-endoperoxide synthase 2 (PTGS2) expression, suggesting it may protect against PTGS2-associated inflammatory disorders, including arthritis." (PMID 41372821, 2025). "Moreover, we revealed that ROBO4 partially suppresses PTGS2-associated inflammatory diseases, including arthritis, edema, and pain in mouse models." (PMID 38762541, 2024). "In addition, Robo4-deficiency in mice exacerbates PTGS2-associated inflammatory diseases, including arthritis, edema, and pain." (PMID 38762541, 2024). "As shown in, 34 essential oil compositions could act on PTGS2 and be linked to arthritis." (PMID 35702766, 2023). "In arthritis, PTGS2 is often up-regulated, leading to increased production of prostaglandins and contributing to the inflammatory response in the affected joints." (PMID 39028255, 2024). "Endothelial PTGS2 contributes to the development of inflammatory diseases, including arthritis and tumors, by enhancing fever, pain, and angiogenesis." (PMID 38762541, 2024). "Prostaglandin-endoperoxide synthase 2 (Ptgs2) had the most interactions (88 drugs) with most of the drugs identified used to treat arthritis, pain, fever, and inflammation." (PMID 37684405, 2023). "Regarding COX-2 expression, they used a collagen-induced arthritis model and found that Ptgs2 mRNA was increased in inflamed hind paw skin and the lumbar spinal cord, but remained absent in the L4 and L5 DRG." (PMID 31969159, 2020). "The results showed a significant stepwise up-expression of chondrogenesis-related genes and arthritis-related gene PTGS2 along with the progression of ONFH." (PMID 30671313, 2019). "Previous studies have demonstrated that PTGS1 and PTGS2 are both highly expressed in the joints of patients with OA, which could provide drug targets for treating arthritis." (PMID 35992559, 2022). "However, the arthritis-related gene PTGS2 was significant stepwise up-expression along with the progression of ONFH which makes it to be a sensitive arthritis-related biomarker of ONFH." (PMID 30671313, 2019). "However, PTGS2 was significantly stepwise up-expressed along with the progression of ONFH which makes it to be a sensitive biomarker in the arthritis process of ONFH." (PMID 30671313, 2019). "PTGS2/Cox-2 is a molecular target for the management of arthritis pain and inflammation." (PMID 23555081, 2013). "Inhibiting PTGS2 activity with medications such as nonsteroidal anti-inflammatory drugs can help alleviate the symptoms of arthritis by reducing inflammation and pain." (PMID 39028255, 2024).
COVID-19 (42 papers, 2020 to 2025). A disease caused by infection with severe acute respiratory syndrome coronavirus 2. "AKT1 is a key participant in COVID-19-related immune inflammation, while PTGS2 inhibition reportedly regulates the excessive inflammatory response of COVID-19." (PMID 41477204, 2025). "Then, five important IADEGs (AXL, MKI67, CDKN3, BCL2 and PTGS2) for severe COVID-19 were screened by random forest analysis." (PMID 37113134, 2023). "Among, AXL, BCL2 and PTGS2 were clustered as a group with high expression in the normal sample and low expression in the COVID-19 sample." (PMID 37113134, 2023). "This research also showed that, out of thirteen targets, the top six (IL-6, PPARG, MAPK3, PTGS2, ICAM1, and MAPK1) are likely to be implicated in the anti-COVID-19 effects of Kochiae Fructus’ active phytomolecules." (PMID 35992697, 2022). "SARS-CoV-2 nucleocapsid binding to PTGS2 prompter resulting in upregulated prostaglandin E2 (PGE2) in COVID-19 patients." (PMID 33717193, 2021). "One proposed step in COVID-19 disease progression involves the nucleocapsid protein binding to the prostaglandin-endoperoxide synthase 2 (PTGS2)/cyclooxygenase-2 (COX-2) promoter and upregulating expression resulting in elevated levels of prostaglandin E2 (PGE2) and other inflammatory molecules." (PMID 33717193, 2021). "Importantly, the PTGS2 inhibitors reported in the study, indomethacin, naproxen, ibuprofen, and thalidomide are currently under the clinical trials for treating COVID-19." (PMID 32566414, 2020). "Besides, with network pharmacology, it was found that the core active compounds in Yupingfeng powder (玉屏风散) regulates multiple signal pathways by binding with ACE2 to ESR1, AR, PTGS2, and other targets to prevent and treat COVID-19." (PMID 33133232, 2020). "Therefore, AXL, MKI67, CDKN3, BCL2 and PTGS2 might be key markers for occurrence and development of severe COVID-19." (PMID 37113134, 2023). "Furthermore, AXL, MKI67, CDKN3, BCL2 and PTGS2 as a marker combination could be used as potential markers to identify severe COVID-19 patients." (PMID 37113134, 2023). "Therefore, ephedra-bitter almond may regulate the expression of PTGS2 in the process of anti-COVID-19 and thus treat respiratory inflammation." (PMID 33292385, 2020). "Surprisingly, HUVECs incubated with severe COVID-19 serum also showed a decrease in the expression of CCL2, IL6, TNFa, PTGS2, and ITGAM compared with the control that received or did not receive pretreatment with PC." (PMID 39066212, 2024). "The top six anti-COVID-19 core targets, IL-6, PPARG, MAPK3, PTGS2, ICAM1, and MAPK1, were molecularly docked with the three key active phytomolecules of Kochiae Fructus." (PMID 35992697, 2022). "A previous study found that Jin Hua Qing Gan Granules regulate multiple signaling pathways via binding targets, such as PTGS2, HSP90AA1, and NCOA2, to prevent COVID-19." (PMID 35891565, 2022). "The potential mechanism of action of HXZQ for COVID-19 is inhibiting SARS-CoV-2 replication, improving immune, and anti-inflammatory, mainly by acting on 3CLpro, PTGS2, AR, HSP90AB1, CAMSAP2, PPARG, NOS2, and other targets." (PMID 36388945, 2022). "The PPI network analysis reveals that multiple targets, including IL-6, PPARG, MAPK3, PTGS2, ICAM1, MAPK1, etc., are involved in the anti-COVID-19 effects of Kochiae Fructus’ active phytomolecules." (PMID 35992697, 2022). "Pathway analysis between Ephedra-Glycyrrhiza and COVID-19 showed that the key targets were TNF-α, IL2, FOS, ALB, and PTGS2." (PMID 33581688, 2021). "Its key compounds including quercetin, kaempferol, 7-O-methylisomucronulatol, baicalein, and formononetin target IL6, MAPK8, PTGS2, PTGS1, and NCOA2 to regulate multiple signal pathways of TCM and play a therapeutic role in the recovery period of COVID-19." (PMID 34335247, 2021). "Among them, IL6, tumor necrosis factor alpha (TNFα), MAPK1, MAPK14, MAPK8, PTGS2, IL2 and PPARG were the predominant targets for Xuebijing to treat COVID-19." (PMID 34539389, 2021).
COVID-19 (continued). "Jinhua Qing Gan Granule (金花清感颗粒) can regulate the signal pathway of PTGS2, HSP90AB1, HSP90AA1, PTGS1, and NCOA2 by combining 2019-nCoV3CL hydrolase and ACE2 to prevent and treat COVID-19." (PMID 33133232, 2020). "Mapping relation examination between COVID-19 and Ephedra-Glycyrrhiza exhibited that the key markers were tumor necrosis factor-α (TNF-α), interleukin-2 (IL-2), albumin (ALB), FOS proto-oncogene, and prostaglandin- endoperoxide synthase 2 (PTGS2)." (PMID 37654998, 2023). "However, early markedly downregulated FcεR1 gene expression observed in Moderate/Severe COVID-19 suggests an inappropriate response, which is further supported by the down regulated targets such as TNF, PTGS2 and IL-1B." (PMID 37261339, 2023). "These compounds may interfere with ACE2 binding to PTGS2, HSP90AB1, AR, CAMSAP2, and other targets that regulate multiple signaling pathways and thus exert a preventive or therapeutic effect on COVID-19." (PMID 34335247, 2021). "In this study, 44 potential targets were obtained through the intersection of the disease targets of COVID-19 and the action targets of AE, which are mainly related to inflammatory or immune factors, such as IL-6, MAPK1, MAPK8, IL1B, RELA, CXCL-8, CCL2, and PTGS2." (PMID 33658066, 2021). "The highly correlated expression of RGS2 with CXCL8, PTGS2, NAMPT, ILB1 and further inflammatory genes in COVID-19 positive nasopharyngeal swabs suggests the involvement of a common regulator, which might explain the distinct classes of COVID-19 symptoms." (PMID 36143181, 2022). "The expression of Prostaglandin-endoperoxide synthase 2 (PTGS2, also known as cyclooxygenase 2) mRNA was increased in PBMC of mild, but not severe COVID-19 patients, whereas the expression of NADPH oxidase (NOX-1) mRNA was reduced in both mild and severe COVID-19 patients compared to healthy donors." (PMID 33692788, 2021). "The direct inhibition of the PTGS2 gene product can be considered as another therapeutic strategy for SARS-CoV-2 infection and could suggest six approved PTGS2 inhibitor drugs for the treatment of COVID-19." (PMID 32566414, 2020).